PIEZO1 (piezo type mechanosensitive ion channel component 1 (Er blood group))
Diseases named in the same sentence as PIEZO1 in open-access papers (continued):
Sharing a sentence is not in itself a finding about the gene and the disease.
periodontitis (4 papers, 2023 to 2025). An acute or chronic inflammatory process that affects the tissues that surround and support the teeth. "To explore the mechanistic role of PIEZO1 in TO-associated periodontitis progression, we performed immunohistochemistry (IHC) staining to analyze the expression of PIEZO1, interleukin (IL)-6, and runt-related transcription factor 2 (RUNX2) in PDL tissue." (PMID 41234768, 2025). "Previous studies demonstrated that TO accelerated periodontitis progression by inhibiting PIEZO1 expression, whereas Yoda1 attenuated alveolar bone loss and inflammation." (PMID 41234768, 2025). "In periodontitis, activated Piezo1 causes a large extracellular Ca2+ influx into macrophages, leading to an increase in M1-type polarization." (PMID 37261355, 2023). "Accordingly, we discovered a novel mechanism underlying periodontitis-related gingival destruction mediated by Piezo1 in this research." (PMID 37261355, 2023). "To summarize, we proposed a novel mechanism underlying periodontitis-induced gingival destruction: macrophages mediate MMPs-degrading collagens via Piezo1, thereby destroying periodontal tissue." (PMID 37261355, 2023). "Through integrated in vitro and in vivo experiments combined with transcriptomic analysis, we found that traumatic occlusion suppressed the expression of PIEZO1 and exacerbated the periodontitis, a process that is closely associated with the MAPK signaling pathway." (PMID 41234768, 2025). "Collectively, these results indicate that local PIEZO1 activation via Yoda1 effectively alleviates periodontal inflammation, preserves tissue integrity, and reduces osteoclast-mediated bone loss in rats with periodontitis aggravated by traumatic occlusion." (PMID 41234768, 2025). "Based on the collective findings, we conclude that traumatic occlusion accelerates the early progression of periodontitis, primarily by impairing mechanotransduction and osteogenic function through PIEZO1 downregulation." (PMID 41234768, 2025). "This PIEZO1-MAPK axis contributes to the inhibition of alveolar bone resorption in traumatic occlusal periodontitis." (PMID 41234768, 2025). "In a rat model combining periodontitis and TO, PIEZO1 expression decreased, with increased inflammation and impaired osteogenesis." (PMID 41234768, 2025). "During periodontitis, reduced mechanical forces impaired Piezo1 function, resulting in unchecked osteoclast activation and pathological resorption." (PMID 41080556, 2025). "To test this, we established an in vivo Sprague-Dawley (SD) rat model of periodontitis combined with traumatic occlusion to evaluate the temporal effects of mechanical trauma on periodontal destruction, PIEZO1 expression, and MAPK signaling." (PMID 41234768, 2025). "In this study, we first identified the critical role of PIEZO1 in the exacerbation of periodontitis due to traumatic occlusion through in vivo assays." (PMID 41234768, 2025). "We discovered that the PIEZO1 expression was markedly elevated in patients with periodontitis through transcriptomic profiling." (PMID 37261355, 2023). "IF results revealed Piezo1 located in macrophages (labeled by CD68) of periodontitis gingival tissues and in the LPS-stimulated RAW264." (PMID 37261355, 2023). "Taken together, Piezo1 is upregulated in macrophages of periodontitis gingival tissues and is induced by LPS." (PMID 37261355, 2023). "Nevertheless, there is still a long way to go before we fully elucidate the biological function and specific mechanism of how Piezo1 mediate MMPs and affects the periodontitis-induced gingival destruction." (PMID 37261355, 2023). "Intriguingly, we found that Piezo1, a mechanosensitive ion channel, was significantly up-regulated in periodontitis group." (PMID 37261355, 2023). "Based on these findings, we hypothesized that the mechanism by which PIEZO1 contributes to the exacerbation of periodontitis by occlusal trauma is related to the MAPK pathway." (PMID 41234768, 2025).
periodontitis (continued). "Activation of PIEZO1 expression may mitigate the exacerbating effect of traumatic occlusion on periodontitis." (PMID 41234768, 2025). "Based on these findings, we hypothesized that PIEZO1 contributes to the exacerbation of periodontitis under traumatic occlusion via modulation of MAPK signaling." (PMID 41234768, 2025). "Overall, TO exacerbates periodontitis by suppressing PIEZO1-MAPK signaling, and PIEZO1 activation may protect periodontal tissues from mechanical and inflammatory damage." (PMID 41234768, 2025). "To confirm whether Piezo1 existed in macrophages, we carried out IF staining in healthy and periodontitis gingival tissues, as well as in RAW264." (PMID 37261355, 2023). "Our results showed that Piezo1 is substantially expressed in periodontitis tissues, and it may operate on macrophages to modulate the immune response." (PMID 37261355, 2023). "Modulation of PIEZO1 activity may therefore ameliorate alveolar bone resorption in periodontitis." (PMID 41234768, 2025). "Our data were consistent with a previous report where the activated Piezo1 contrarily triggered M1 macrophage polarization in response to LPS, triggered overproduction of proinflammatory cytokines (e.g. TNF-α and IL-1β) and ultimately contributed to collagen degradation in periodontitis." (PMID 38303078, 2024).
prostate tumor (4 papers, 2020 to 2024). "The expression of Piezo1 within prostate tumors is significantly higher than in normal tissues." (PMID 36837670, 2023). "Importantly, the knockdown of Piezo1 channel decreased cell growth and migration in vitro and suppressed the growth of prostate tumors injected in nude mice." (PMID 32635333, 2020). "Notably, though, other studies reported that Piezo1 is upregulated in prostate tumor cell lines such as DU145 and PC3 cells, as well as in human prostate tumor biopsies, where it plays a crucial role in the epithelial-to-mesenchymal transition essential for tumor progression." (PMID 38581527, 2024). "Furthermore, the expression of Piezo1 is largely elevated, both at mRNA and protein levels, in human prostate tumor samples compared to non-malignant tissues." (PMID 32635333, 2020).
acute pancreatitis (3 papers, 2018 to 2024). An acute inflammatory process that leads to necrosis of the pancreatic parenchyma. "Roles for calcium entry and plasma membrane calcium exporters in acute pancreatitis have been shown, including calcium entry through the Orai1 and Piezo1/TRPV4 transporters." (PMID 39010833, 2024). "In the acinar cells of patients with acute pancreatitis, the Piezo1 of the acinar cells is upregulated and induced PLA2 to activate the TRPV4 channel to cause the continuous increase of Ca2+ and damage the mitochondrial function." (PMID 35154133, 2022). "In order to demonstrate the essential role of Piezo1 in developing acute pancreatitis, we examined the effects of high intraductal pressure in Piezo1aci KO mice." (PMID 29712913, 2018).
airway hyperresponsiveness (3 papers, 2024 to 2025). "Recent studies have indicated that inhibiting Piezo1 signaling pathways can partially alleviate airway hyperresponsiveness in animal models, suggesting that Piezo1 may be a new target for treating diseases with airway hyperreactivity." (PMID 41195420, 2025).
ankylosing spondylitis (3 papers, 2025 to 2026). An autoimmune chronic inflammatory disorder characterized by inflammation in the vertebral joints of the spine and sacroiliac joints. "This study aimed to investigate the role of Piezo1 in the immune-inflammatory response during the pathogenesis of ankylosing spondylitis (AS) and its underlying mechanisms." (PMID 41507149, 2026). "According to reports, Piezo1 acts as a regulatory factor in osteoblasts by sensing mechanical loads, affecting bone remodeling and mediating pathological new bone formation in ankylosing spondylitis through this mechanism." (PMID 40753437, 2025). "Piezo1-mediated mechanotransduction enhances pathological new bone formation at the entheses in ankylosing spondylitis (AS)." (PMID 40169556, 2025).
aortic aneurysm (3 papers, 2022 to 2024). A ruptured aneurysm located in the wall of the proximal portion of the descending aorta proceeding from the arch of the aorta. "Recent studies identified Piezo1 as the culprit for VSMC maladaptive mechanosensation in aortic aneurysm, a lethal vascular disease that predominantly affects the aged population." (PMID 37941511, 2024). "The enriched expression of MMP3 in VSMCs were previously shown to be regulated by Piezo1 activation in VSMC of aortic aneurysm, suggesting that the old and AngII‐treated young cells are associated with dysfunction in mechanosensory behaviors and high risk of cardiovascular disease development." (PMID 37941511, 2024). "We further delved into the signals that upregulated Piezo‐1 in VSMC by probing for α‐actinin 2, as we have previously shown that this actin fiber crosslinker activates Piezo‐1 expression in VSMC, thereon modulating VSMC responses in aortic aneurysms." (PMID 38825882, 2024).
cerebral malaria (3 papers, 2023 to 2025). A sequestration of Plasmodium falciparum in the brain, which can cause coma and/or seizures. "Moreover, in vivo CRISPR-engineered animal models, including mice carrying humanized RBCs or specific allelic variants such as PIEZO1 gain-of-function mutations-have provided critical insights into the role of host genes in modulating vascular pathology and cerebral malaria outcomes." (PMID 40993672, 2025). "RBCs mediate protection against Plasmodium infection and cerebral malaria through gain-of-function PIEZO1, while T cells also contribute to the prevention of cerebral complications." (PMID 40993672, 2025). "In the same line, Yoda1, as well as GOF PIEZO1 mutations (slowing down channel inactivation) cause RBC dehydration in a defined minimal medium and was shown to confer resistance against cerebral malaria." (PMID 37071200, 2023). "Piezo1 R2482H mice show no damage of the blood–brain barrier, while wild type mice succumb to cerebral malaria leading to death within 5–7 days post infection." (PMID 37071200, 2023).
cervical carcinoma (3 papers, 2025). A carcinoma arising from either the exocervical squamous epithelium or the endocervical glandular epithelium. "Silencing Piezo1 significantly reduced cervical cancer cell invasion and migration, while activation with the selective agonist enhanced these processes." (PMID 40361464, 2025). "Elevated expression of Piezo1 was observed in cervical cancer tissues and cells, particularly in patients with lymph node metastasis." (PMID 40361464, 2025). "The mechanosensitive ion channel Piezo1 has been identified as a potential prognostic and therapeutic target in cervical cancer." (PMID 40361464, 2025). "It was found that activation of Piezo1 is capable of regulating the release of extracellular ATP, which can enhance invasion, migration, and pseudopodium formation in cervical cancer." (PMID 40361464, 2025). "Histopathological analyses show markedly elevated Piezo1 expression in cervical carcinoma, particularly in lymph-node–positive cases." (PMID 40821847, 2025). "The results of the cited study suggest that Piezo1 contributes to cervical cancer progression by facilitating ATP release and could serve as a promising target for therapeutic and prognostic applications." (PMID 40361464, 2025).
chronic kidney disease (3 papers, 2022 to 2024). Impairment of the renal function secondary to chronic kidney damage persisting for three or more months. "Moreover, searching Piezo1 in the single cell RNAsequencing data from the Kidney Precision Medicine Project revealed a disease-associated expression of the channel (mean expression: healthy controls: 1.45; chronic kidney disease (CKD): 1.73)." (PMID 39548228, 2024). "Also, searching publicly available human data (KPMP) revealed an increase of Piezo1 in podocytes in chronic kidney disease." (PMID 39548228, 2024). "Our unpublished data obtained from a renal ischemia/reperfusion (I/R) injury model showed increased mRNA expression levels of Piezo1 in 24-hour I/R injury and in I/R-induced chronic kidney disease rat models (unpublished data), supporting a role of Piezo1 in the early stage of renal injury." (PMID 35230979, 2022).
Cirrhosis (3 papers, 2025 to 2026). A chronic disorder of the liver in which liver tissue becomes scarred and is partially replaced by regenerative nodules and fibrotic tissue resulting in loss of liver function. "Additionally, higher expression levels of Piezo1 in the hepatic portal vein area could be linked to the biological effects stemming from portal hypertension in patients with cirrhosis." (PMID 41017814, 2025).
colon adenocarcinoma (3 papers, 2020 to 2025). "Similar to our colon adenocarcinoma cell lines, the metastatic melanoma cell line exhibited a decreased abundance of Piezo1 compared to cells from the primary tumor." (PMID 36080197, 2022). "The result showed that Piezo1 expression was higher in most of low-differentiation colon adenocarcinoma tissues compared to high-differentiation colon adenocarcinoma tissues and adjacent normal low-differentiation colon tissues." (PMID 32152662, 2020). "To further investigate our findings, we measured Piezo1 expression in three low-differentiation colon adenocarcinoma tissues." (PMID 32152662, 2020).
dementia (3 papers, 2018 to 2025). Loss of intellectual abilities interfering with an individual's social and occupational functions. "Recent studies have disclosed a critical role for the Piezo1 channel in modifying AD and, in addition, a positive association of the Piezo1 channel activity in red blood cells (RBCs) with the early development of AD-related dementia." (PMID 41415893, 2025). "In addition to the role in modifying AD, emerging evidence suggests an increase in the Piezo1 channel activity in RBCs and supports a positive association of such increased Piezo1 channel activity with the early development of AD-related dementia." (PMID 41415893, 2025). "Interestingly, repeated urinary tract infections with Escherichia coli bacteria, a common comorbidity in elderly people with dementia, caused further elevations in Piezo1 channel expression in the hippocampus and cortex of TgF344-AD rats." (PMID 30405400, 2018). "Recently, the role of Piezo1 in the mechanisms of age-related physiological and pathological dementias, like in the course of Alzheimer’s disease (AD) and of other origins, is postulated." (PMID 36173070, 2023). "In this opinion piece, we summarize the recent findings and debate whether the Piezo1 channel is a feasible target for formulating strategies for modifying AD and detecting AD-related dementia at the early stage." (PMID 41415893, 2025). "While considering the role of Pizeo1 in various dementias, it should also be stressed that there is a potential interaction of Piezo1 with the metabolic status of cells, and its changes may be crucial in cognitive declines." (PMID 36173070, 2023). "However, further research is anticipated to gain a better understanding of the Piezo1 channel mechanism of AD and more information to inform whether the Piezo1 channel can be used as a feasible target for formulating strategies to modify AD and detect AD-related dementia at an early stage." (PMID 41415893, 2025).
diabetic neuropathy (3 papers, 2023 to 2025). A chronic, pathological complication associated with diabetes mellitus, where nerve damages are incurred due to diabetic microvascular injury involving small blood vessels that supply these nerves, resulting in peripheral and/or autonomic nerve dysfunction. "The upregulation of TRPV4/Piezo1 transcription by TGFβ2 predicts exaggerated responsiveness to mechanical loading, as reported for chemotherapy, neuropathic pain, cancer, and diabetic neuropathy." (PMID 39574569, 2025). "The upregulation of TRPV4/PIEZO1 transcription by TGFβ2 predicts exaggerated responsiveness of the outflow pathway to mechanical loading, as reported for TRPV4-dependent mechanical hyperalgesia in chemotherapy, neuropathic pain, cancer, and diabetic neuropathy." (PMID 40552711, 2025).
disc degeneration (3 papers, 2024 to 2026). "During the pathogenesis of disc degeneration, a stiff extracellular matrix was found to activate PIEZO1 channels and enhance intracellular Ca2+ levels in the nucleus pulposus." (PMID 38494915, 2024). "In this study, we found that Piezo1 is a key regulator of iron metabolism in disc degeneration." (PMID 38553442, 2024).
E coli infection (3 papers, 2018 to 2021). "coli infection, the production of mROS and cellular ROS in response to LPS treatment or E. coli infection, as well as the ability of bacterial phagocytosis and clearance in Piezo1-deficient BMDMs." (PMID 34112781, 2021). "We found that LPS stimulation or E. coli infection promotes the engagement of the corresponding TLR4 receptor with the mechanical sensor Piezo1 to induce calcium influx." (PMID 34112781, 2021). "This suggests that whilst peripheral E. coli infection alone can upregulate astrocytic Piezo1; Aβ1-42 CMM and in vivo amyloid plaque pathology are stronger triggers of mechanosensing Piezo1 channel expression in reactive astrocytes." (PMID 30405400, 2018). "Consistently, AFM measurement showed that overexpression of RacG12V in Piezo1-deficient BMDM resulted in higher cellular stiffness compared with that of Piezo1-deficient BMDMs with or without E. coli infection." (PMID 34112781, 2021). "Interestingly, loss of Mst1/2 or Mst1/2 kinases inhibitor treatment abrogated filopodia formation or actin accumulation at sites of bacteria induced by LPS or the Piezo1 agonist Yoda1 treatment or E. coli infection." (PMID 34112781, 2021). "Unlike the cerebral cortex, upregulations in Piezo1 expression were measured in the hippocampal CA1 region (28 ± 5%) in response to peripheral E. coli infection at 12 months of age in iWT rats." (PMID 30405400, 2018). "Interestingly, peripheral E. coli infections did not increase Piezo1 expression in the prefrontal cortex of WT rats at 12 months (15 ± 3%) nor at 18 months (12 ± 3%) of age compared to WT controls." (PMID 30405400, 2018).